HTT (huntingtin)
Diseases named in the same sentence as HTT in open-access papers (continued):
Sharing a sentence is not in itself a finding about the gene and the disease.
Huntington disease (continued). "Huntington’s disease (HD) is a progressive, inherited neurodegenerative disorder caused by a CAG repeat expansion in the huntingtin gene, which results in the production of mutant huntingtin (mHTT) protein with an abnormally long polyglutamine (polyQ) expansion (≥36 CAG repeats)." (PMID 36839842, 2023). "Huntington's disease (HD) is an incurable inherited brain disorder characterised by massive degeneration of striatal neurons, which correlates with abnormal accumulation of misfolded mutant huntingtin (mHTT) protein." (PMID 37535170, 2023). "For example, in Huntington's Disease (HD), an autosomal dominant genetic disorder characterized by the expansion of the CAG repeats in the gene encoding for the huntingtin protein, important perturbations in both central nervous system (CNS) and whole-body cholesterol metabolism have been described." (PMID 36119674, 2022). "In Huntington’s disease models, mutant huntingtin (Htt) disrupts Nrf2 signaling, which contributes to impaired mitochondrial dynamics and may enhance susceptibility to oxidative stress in striatal cells." (PMID 35883884, 2022). "Taken together, the data were broadly consistent with the view that the EEG activity of Huntington’s disease patients at baseline may reflect downstream consequences of the altered HTT gene driving the disease." (PMID 35774187, 2022). "It is well known that autophagy is a fundamental process to eliminate protein aggregations such as Aβ and tau in AD; α-synuclein (α-syn) in PD; huntingtin in Huntington’s disease (HD); or TAR DNA-binding protein 43 (TDP-43) in amyotrophic lateral sclerosis (ALS)." (PMID 35897658, 2022). "To investigate the effect of reversible inhibition of CPT1, we used a well-established Drosophila model for Huntington’s disease (Q128HD-FL) in which the human HTT complementary DNA (cDNA) with 128 glutamine repeats is expressed in all neuronal tissues (genotype: elav-Gal4/+; UAS-hFLHD-128Q/+;)." (PMID 35630602, 2022). "Interestingly, expression of mutant huntingtin, the disease protein in Huntington ́s disease (HD), was also shown to affect maturation of BMMC." (PMID 35558088, 2022). "Huntington's disease (HD) is an autosomal dominant neurodegenerative disease caused by a cytosine adenine guanine (CAG) trinucleotide repeat expansion in the huntingtin gene, resulting in the production of the toxic mutant huntingtin protein." (PMID 36793800, 2022). "Likewise, activation of Hsp70 with YM-1 also modulated huntingtin proteostasis by reducing aggregation of huntingtin, which hence holds potential for treating Huntington’s disease." (PMID 36498892, 2022). "However, the contribution of soluble and intracellular protein aggregates derived from mutant huntingtin (mHtt) to the pathogenesis of Huntington’s disease is still unclear." (PMID 36551756, 2022). "Huntington’s disease (HD) is an autosomal dominant neurodegenerative disorder caused by expanded CAG repeats in exon 1 of the huntingtin gene (HTT, also called IT15), resulting in extended polyglutamine (polyQ) tracts in the N-terminal of the HTT protein." (PMID 35224690, 2022). "In another study of Huntington’s Disease (HD), patients were found to have reduced proteolytic activity in the brain and other tissues, leading to intraneuronal nuclear protein aggregates of mutant huntingtin." (PMID 35892577, 2022). "Neurodegenerative disease processes have been shown to involve dysregulation of several relevant proteins, such as α-synuclein (Parkinson’s and Lewy body diseases), tau, and amyloid beta (Aβ) (Alzheimer’s disease) huntingtin (Huntington’s disease), and TDP-43 (Frontotemporal dementia)." (PMID 36319674, 2022). "Huntington’s disease (HD) is a fatal inherited neurodegenerative disorder driven by a CAG (cytosine, adenine, guanine) trinucleotide expansion in exon 1 of HTT, the gene that encodes huntingtin protein." (PMID 36078156, 2022). "In Huntington's disease neurons, mutant HTT and HTT form clusters at HTT gene loci." (PMID 36458209, 2022).
Huntington disease (continued). "For instance, the activation of calpains and caspases was reported as one of the cellular changes in Huntington’s disease, where proteases are possibly activated to cope with the aggregates, although they cleave the huntingtin aggregates into more toxic smaller fragments." (PMID 35974087, 2022). "Indeed, most of the proteins found downregulated in the striatum of Huntington’s disease mice in SH conditions, prior to motor symptoms, are known to interact with huntingtin protein." (PMID 36523271, 2022). "Fluorescent muscle aggregates accumulate with age in a strain expressing Q40::YFP in muscle, mimicking the polyglutamine array expansion threshold for huntingtin protein, i.e., the array length sufficient to elicit symptoms of Huntington’s disease in humans and paralysis in nematodes." (PMID 35890250, 2022). "In animal models of Huntington’s disease, intravenous injection of a novel AAV encoding an artificial miR that targets the huntingtin (HTT) gene yielded extensive knockdown of HTT across multiple brain regions with the highest transduction observed in the striatum." (PMID 36601439, 2022). "Researchers have cited the aggregation of TDP-43 proteins in Amyotrophic Lateral Sclerosis (ALS), amyloid-beta in Alzheimer disease (AD), α-synuclein in Parkinson disease (PD), or polyglutamine-expanded Huntingtin protein in Huntington disease (HD), for example." (PMID 35409239, 2022). "Huntington disease (HD) is an autosomal dominant neurodegenerative disorder, caused by an expansion of an unstable trinucleotide CAG repeat in the exon 1 of HTT gene, which translates into an elongated polyglutamine stretch in Huntingtin protein." (PMID 35055435, 2022). "Huntington’s disease (HD) is an autosomal dominant neurodegenerative disorder caused by the CAG repeat in the exon 1 of the huntingtin gene, which encodes for huntingtin (HTT), a cytoplasmic protein ubiquitously expressed in all cells of the body." (PMID 35887162, 2022). "Huntington’s disease (HD) is a rare, inherited, and progressive neurodegenerative disease caused by CAG-repeat expansion in exon 1 of the huntingtin gene, leading to the expression of mutant huntingtin (Htt) protein with expanded polyglutamine (polyQ) repeat." (PMID 36101390, 2022). "Long non-coding RNAs and Huntington’s disease (HD, Huntington’s disease; mHTT, mutant Huntingtin)." (PMID 36185471, 2022). "Here, we investigated whether gut bacteria affect the progression of Huntington’s disease (HD) in transgenic Drosophila melanogaster (fruit fly) models expressing full-length or N-terminal fragments of human mutant huntingtin (HTT) protein." (PMID 35757549, 2022). "Pathological marks of this condition including Parkinson's disease (PD), Alzheimer's disease (AD) and Huntington's disease (HD), are deposits of mutant proteins like α-synuclein, amyloidβ (Aβ) and mutant huntingtin (Htt), respectively in the affected regions of brain." (PMID 36532555, 2022). "Huntington’s disease (HD) is an autosomal dominant neurodegenerative disorder characterised by an aberrant expansion of the cytosine adenine guanine (CAG) triplet in the polyglutamine region of the huntingtin (HTT) gene." (PMID 36232693, 2022). "The Huntington disease gene HTT was cloned in 1993, 10 years after the linkage of the gene to chromosome 4 in 1983 because this gene was located near the chromosome 4p terminus, which was composed of many repetitive elements where a considerable number of recombination events in meiosis occur." (PMID 34159713, 2021). "Huntington’s disease (HD) is a progressive, autosomal dominantly inherited neurodegenerative disease caused by an expansion of a trinucleotide (CAG) repeat in the huntingtin (HTT) gene." (PMID 34115782, 2021). "PIAS1 may serve to regulate the accumulation of Huntingtin (HTT) proteins and its modulation in neurons, which can alter Huntington's disease (HD)-associated phenotypes in vivo." (PMID 33759814, 2021).
Huntington disease (continued). "Huntington disease (HD; OMIM 143100) is an autosomal, dominantly inherited, progressive, neurodegenerative disorder caused by an expansion of a coding CAG trinucleotide repeat in the exon 1 of huntingtin (HTT) gene." (PMID 33567536, 2021). "Activation of this pathway in neurons via insulin growth factor 1 is protective against huntingtin-induced toxicity in experimental Huntington’s disease models; however, contrasting observations were made in the peripheral immune cell compartment of Huntington’s disease patients." (PMID 34838047, 2021). "Huntington’s disease is largely considered a neurodegenerative disease, with very little impact on development due to late onset of symptoms and the ability of mHtt expression to rescue embryonic lethality in HTT-null mice." (PMID 35095429, 2021). "Huntington’s disease (HD) is an autosomal dominant, progressive neurodegenerative disease caused by an expanded CAG repeat/polyglutamine (polyQ) tract beyond 35 repeats within the first exon of the huntingtin (HTT) gene." (PMID 34458253, 2021). "Huntington’s disease (HD) is an autosomal dominant trinucleotide repeat pathology caused by an unstable expansion of CAG repeats, the trinucleotide encoding the amino acid glutamine in the exon 1 of the HUNTINGTIN gene." (PMID 33420088, 2021). "Huntington’s disease (HD) is an autosomal dominant neurodegenerative disease caused by a polymorphic CAG repeat extension in exon 1 of the huntingtin gene, which encodes for mutant Huntingtin (mHTT) protein." (PMID 33546471, 2021). "Huntington disease is a monogenic disease that is caused by a CAG trinucleotide repeat expansion in exon 1 of the HTT gene (also known as the IT15 gene), which encodes the large, 348 kDa protein huntingtin (HTT)." (PMID 34211373, 2021). "Our collaborators, Prof David Rubinsztein and coworkers at Cambridge University, using their zebrafish larvae models of tauopathies and Huntington’s disease, showed that treatment of these fish with sildenafil for four days reduced the levels of the mutant tau and huntingtin." (PMID 34067263, 2021). "The key role of autophagy in the maintenance of cellular survival and in the suppression of neurodegeneration has been evaluated in Alzheimer’s, Parkinson’s, and Huntington’s diseases, which are accompanied by the accumulation of beta-amyloid, alpha-synuclein, and huntingtin, respectively." (PMID 34685538, 2021). "Huntington's disease (HD) is another common neurodegenerative condition with motor deficits, which is associated with mutations of the expanded cytosine-adenine-guanine (CAG) repeats in the huntingtin (HTT) gene." (PMID 34389067, 2021). "Huntington’s disease (HD) is a fatal, autosomal dominantly inherited neurodegenerative disorder caused by the expansion of a polyglutamine (polyQ)-coding CAG repeat within the mutant huntingtin gene." (PMID 33809220, 2021). "Strategies aimed at lowering HTT protein levels, by targeting either the huntingtin gene or the transcript, have become a major focus of therapeutic development for Huntington’s disease, with antisense oligonucleotides having progressed to a phase 3 clinical trial." (PMID 33604571, 2021). "Huntington’s disease (HD) is an incurable autosomal-dominant genetic disease caused by an abnormal expansion (of variable number) of CAG repeats in exon 1 of the HTT gene, which encodes for the huntingtin protein (htt)." (PMID 35053183, 2021). "Although wild type huntingtin protein can interact with REST/NRSF and increase BDNF expression, mutant huntingtin, which has been found in Huntington’s disease patients, loses the ability to interact with REST/NRSF, resulting in repression of Bdnf and other REST/NRSF target genes." (PMID 34977362, 2021).
Huntington disease (continued). "Many of these mammalian proteins are associated with neurodegenerative disorders, such as amyloid precursor protein in Alzheimer’s disease (AD), ataxin in amyotrophic lateral sclerosis (ALS), huntingtin in Huntington’s disease (HD) and a-synuclein in Parkinson’s disease (PD)." (PMID 34209482, 2021). "Huntingtin is an essential protein for early embryonic development in many species, encoded by HTT, a gene whose major characteristic, when mutated, is to be associated to the Huntington disease (HD) (UniProt accession code P42858)." (PMID 33809039, 2021). "The two top biological networks of these targets are centered on two proteins associated with neurodegeneration, the amyloid precursor protein APP that is associated with Alzheimer’ disease and Huntingtin (HTT), a genetic mutation associated with Huntington’s disease." (PMID 34571817, 2021). "For example, Alzheimer’s disease (AD), Parkinson’s disease (PD), Amyotrophic Lateral Sclerosis (ALS) and Huntington’s disease all exhibit protein aggregate pathology in the form of neurofibrillary tangles, Lewy bodies, inclusion bodies, and mutant Huntingtin aggregates, respectively." (PMID 34208502, 2021). "Huntington’s disease (HD) is a monogenic hereditary neurodegenerative disorder caused by the expansion of a glutamine (Q, CAG) stretch in the first exon of the protein huntingtin (HTT)." (PMID 34720872, 2021). "To investigate the contributions of glia to Huntington's disease (HD), we profiled the gene expression alterations of Drosophila expressing human mutant Huntingtin (mHTT) in either glia or neurons and compared these changes to what is observed in HD human and HD mice striata." (PMID 33871358, 2021). "However, MW8 did immunoprecipitate full-length HTT from Huntington’s disease knock-in mouse brain lysates." (PMID 33604571, 2021). "Huntington’s disease (HD) is a progressive neurodegenerative disorder, of autosomal dominant inheritance, caused by the expansion of a CAG repeat, within exon 1 of the huntingtin (HTT) gene." (PMID 33907289, 2021). "Huntington’s disease is a dominantly inherited neurodegenerative disorder caused by the expansion of a CAG repeat, encoding for the amino acid glutamine (Q), present in the first exon of the protein huntingtin." (PMID 34720872, 2021). "Fluid biomarkers for proteins relevant to other neurological conditions are becoming available—for example mutant huntingtin for Huntington’s disease or frataxin for Friedreich’s ataxia—although assays for some proteinopathies such as α-synuclein and TDP-43 remain a challenge." (PMID 33846962, 2021). "Huntington’s disease (HD) is a devastating autosomal dominant neurodegenerative disorder caused by an expansion of CAG (cytosine-adenine-guanine) trinucleotide repeat in the huntingtin gene (HTT, located on chromosome 4p16.3), encoding for huntingtin protein." (PMID 33935934, 2021). "Huntington's disease (HD) is a progressive neurodegenerative disease caused by expanded CAG mutation in the Huntington gene (HTT), which leads to an expanded polyglutamine stretch in the huntingtin protein (Htt)." (PMID 34336127, 2021). "Huntington’s disease (HD) is a debilitating genetic disorder caused by an expansion of the CAG (cytosine, adenine, guanine) repeat within the huntingtin (HTT) gene, and characterised by motor, cognitive and psychiatric symptoms associated with neuropathological decline." (PMID 33865029, 2021). "Huntington’s disease (HD), an autosomal dominant neurodegenerative disease, is caused by an accumulation of the trinucleotide CAG repeats within the HTT gene, resulting in an expansion of polyglutamine repeats in the huntingtin protein (mutant huntingtin, mtHtt)." (PMID 34502501, 2021). "Huntington’s disease (HD) is characterized by an expanded polyglutamine (PolyQ) chain in the HTT proteins, which is caused by the repeat expansion of CAG trinucleotide in the first exon of the HTT gene." (PMID 33562649, 2021).
Huntington disease (continued). "Huntington’s disease (HD) is an autosomal dominant, chronic, incurable neurodegenerative disease caused by an anomalous expansion of the trinucleotide sequence CAG, which encodes the amino acid glutamine within the Huntingtin gene (HTT;)." (PMID 34073127, 2021). "Huntington’s disease (HD) is an autosomal dominant neurodegenerative disease which profoundly affects the corpus striatum of the brain; it results from expansion of polyglutamine repeats in the protein huntingtin." (PMID 34573100, 2021). "Huntington Disease (HD) is a dominant, lethal neurodegenerative disorder caused by the abnormal expansion (>35 copies) of a CAG triplet located in exon 1 of the HTT gene encoding the huntingtin protein (Htt)." (PMID 34945781, 2021). "Huntington’s disease (HD) is a neurodegenerative disorder caused by a poly-CAG expansion in the first exon of the HTT gene, resulting in an extended poly-glutamine tract in the N-terminal domain of the Huntingtin (Htt) protein product." (PMID 34732320, 2021). "Huntington’s disease (HD) is a deadly, dominantly-inherited neurodegenerative disorder that is caused by expansion of CAG repeats in the poly-glutamine (polyQ) tract (> 35 repeats) in the huntingtin (HTT) gene." (PMID 32611447, 2020). "The presence of the mutant HTT gene did not have any effect on total huntingtin concentrations; total huntingtin concentrations in CSF have not, to our knowledge, been examined in controls and Huntington's disease mutation carriers before." (PMID 32470422, 2020). "Additionally, there is an intriguingly low cancer incidence in human patients with Huntington's disease and a body of work examining the role of mutant and wild-type huntingtin protein in cancer development and progression." (PMID 32258065, 2020). "Huntington’s disease, characterised by chorea, dystonia, incoordination, and cognitive decline, is caused by CAG trinucleotide repeat expansion in the huntingtin gene, manifesting in polyglutamine repeats in the huntingtin protein." (PMID 32316192, 2020). "The two proteins include the exon 1 fragment of Huntingtin (Httex1), which accumulates into intraneuronal inclusions in Huntington Disease and a dipeptide polymer of glycine-alanine (polyGA) that forms intraneuronal inclusions in Amyotrophic Lateral Sclerosis (ALS) and Frontotemporal Dementia (FTD)." (PMID 32857759, 2020). "Noted examples include ɑ-Synuclein Lewy bodies in Parkinson’s disease, Tau neurofibrillary tangles in Alzheimer’s disease, Superoxide dismutase 1 (SOD1)-mediated aggregates in Amyotrophic Lateral Sclerosis, and mutant Huntingtin protein aggregates in Huntington’s disease." (PMID 32998777, 2020). "Huntington’s disease is caused by CAG repeat expansion in the HTT gene, encoding for mHTT (No authors listed, 1993), with expanded polyglutamine (polyQ) stretch at the N-terminal." (PMID 33072759, 2020). "Huntington’s disease (HD) is a dominant inherited progressive neurodegenerative disorder caused by expansion of a CAG repeat, coding a polyglutamine repeat within the N-terminal region of huntingtin protein." (PMID 32513388, 2020). "Furthermore, it was shown that in Huntington’s disease patients’ neurons, the retrograde transport of NTRK2, and therefore BDNF signaling, is impaired by mutated HTT." (PMID 32151030, 2020). "Huntington's disease (HD) is a neurodegenerative disorder caused by the expansion of a CAG repeat sequence in exon 1 in the Huntingtin gene, leading to the expression of mutant huntingtin (mHtt) protein containing an expanded polyglutamine stretch." (PMID 32017180, 2020). "Huntington’s Disease (HD) is an inherited neurodegenerative disease caused by a single mutation in the IT15 gene, known as huntingtin (HTT), that generates a toxic huntingtin protein (mHTT), leading to the dysfunction or death of medium spiny neurons (MSNs) from the striatum." (PMID 32848630, 2020).